ATF6 (activating transcription factor 6)
Diseases named in the same sentence as ATF6 in open-access papers (continued):
Sharing a sentence is not in itself a finding about the gene and the disease.
cardiovascular disease (5 papers, 2020 to 2023). "Certain single nucleotide polymorphisms that increase the amount of ATF6α signaling have been associated with increases in blood cholesterol in patients at risk of cardiovascular disease, potentially because ATF6α may interact with the SREBP2 lipid biosynthesis pathway." (PMID 32046286, 2020). "For example, naringenin is a regulator for cholesterol efflux that enhances lipoprotein profiles and protects against cardiovascular disease, and that regulation is mediated by the ATF6 branch of the ER stress and PI3K/AKT pathway." (PMID 35502176, 2022).
kidney disease (5 papers, 2016 to 2023). "The function of ATF6 can be adaptive or maladaptive, depending on the different contexts, and few studies have been published regarding the role of ATF6 in the kidney disease." (PMID 37838725, 2023). "Few studies have been published regarding the role of ATF6 in kidney disease." (PMID 33671535, 2021). "This review aimed to dissect the cellular response to ER stress which manifests with activation of the unfolded protein response (UPR) with its major branches, namely PERK, IRE1α, ATF6 and the interplay between ER and mitochondria in the pathophysiology of kidney disease." (PMID 33067928, 2020).
liver (5 papers, 2019 to 2022). "High expression of ATF6 is observed in recurrent tumors and correlated with poor prognosis in colon cancer." (PMID 32034256, 2020). "In the transition period, bovine hepatocytes experience severe ER stress together with an upregulation in lipogenic gene expression, resulting in periparturient diseases (e.g., severe fatty liver) and an observed increase in the protein expression levels of phosphorylated -PERK, p-IRE1, and ATF6." (PMID 34237916, 2022).
neurological diseases (3 papers, 2020 to 2024). "Dysregulation or loss of ATF6 during development and in adulthood is thought to contribute to neurological disorders." (PMID 31852729, 2020). "Ultimately, these observations suggest that neurons are susceptible to unfolded protein stress at the ER, and that ATF6 could be an important target in modifying neurological diseases." (PMID 31852729, 2020).
adenocarcinoma (2 papers, 2013 to 2024). A common cancer characterized by the presence of malignant glandular cells. "We therefore decided to explore the activation of ATF6 by IHC in the DEN-induced tumors, as well as in the various human adenocarcinomas." (PMID 24339898, 2013).
benign tumors (1 paper, 2020). "The expression of GRP78, ATF6 and PERK were not different between benign tumors and normal tissues." (PMID 32034256, 2020).
retinopathy (1 paper, 2025). "To investigate the role of Atf6 in pathological retinal angiogenesis, we subjected Atf6−/− mice to the oxygen-induced retinopathy (OIR) paradigm." (PMID 41006433, 2025).
ATF6 also shares sentences with these, for which no sentence is quoted: hyperlipidemia (4 papers); liposarcoma (4); alcoholic fatty liver disease (2); congenital cataracts (2); Crohn disease (2); esophageal cancer (2); fibrosis (2); Hyperinsulinemia (2); kidney damage (2); ulcerative colitis (2); abdominal aortic aneurysm (1); acute kidney injury (1); alcoholic liver diseases (1); alcoholism (1); Anxiety (1); bacterial infections (1); Best disease (1); bone cancer (1); Brain atrophy (1); brain disorder (1); breast adenocarcinoma (1); cerebral infarction (1); cholangiocarcinoma (1); clear cell renal cell carcinoma (1); colon (1); complement deficiency (1); cutaneous squamous cell carcinoma (1); dwarfism (1); dysplasia (1); endometrial adenocarcinoma (1).
A further 38 diseases each share a sentence with ATF6 in 1 paper.